FPR2 (formyl peptide receptor 2)
Diseases named in the same sentence as FPR2 in open-access papers (continued):
Sharing a sentence is not in itself a finding about the gene and the disease.
Obesity (20 papers, 2017 to 2026). Accumulation of substantial excess body fat. "FPR2 in bone marrow influences obesity and associated inflammation by regulating muscle energy expenditure, macrophage chemotaxis, and M1 polarization." (PMID 36686646, 2022). "According to another report, FPR2 deficiency relieved inflammation by suppressing M1 polarization and inflammation mediated by macrophage chemotaxis in obesity-related inflammation and atherosclerosis." (PMID 36142517, 2022). "Mice with systemic deficiency of Fpr2 demonstrate reduced severity of HFD-induced obesity, insulin resistance, hyperglycemia, hyperlipidemia, and hepatic steatosis." (PMID 32038501, 2020). "Moreover, a recent report suggested that the deletion of resolution sensor ALX/FPR2 is associated with the development of diastolic dysfunction related with obesity in mice with HFpEF, supporting the concept of non-resolving inflammation in HFpEF." (PMID 34707513, 2021). "FPR2-null mice with HFD-induced obesity also exhibited reduced tissue and systemic inflammation by inhibiting macrophage infiltration and macrophage M1 polarization." (PMID 40733247, 2025). "Upregulated FPR2 expression was observed in the white adipose tissue of mice with HFD-induced obesity and db/db mice." (PMID 40733247, 2025). "The authors also noted that FPR2-expressing myeloid cells exacerbated HFD-induced obesity, metabolic disturbances, and inflammation." (PMID 40733247, 2025). "It was shown that Fpr2 on the immune cells involved in diet-induced obesity, metabolic disturbances, and inflammation." (PMID 36984693, 2023). "The authors also found that myeloid Fpr2 played an important role in diabetic-induced obesity, IR, and glucose/lipid dysmetabolism." (PMID 36984693, 2023). "It was also revealed that Fpr2 deficiency reduced body weight gain in mice fed HFD and inhibited macrophage infiltration and M1 polarization in mice with diet-induced obesity." (PMID 36984693, 2023). "The aim of the work was to investigate NADPH-oxidase-dependent generation of reactive oxygen species (ROS) initiated though membrane formyl peptide receptors (Fpr1, Fpr2) in bone-marrow granulocytes of obesity-resistant mice (ORM) fed high-fat diets (HFD)." (PMID 36984693, 2023). "We analyzed the generation of reactive oxygen species (ROS) initiated though membrane formyl peptide receptors (Fpr1, Fpr2) in bone-marrow granulocytes of obesity-resistant mice (ORM)." (PMID 36984693, 2023). "Bone marrow transplantations between wild-type and Fpr2-/- mice and myeloid-specific Fpr2 deletion demonstrated that Fpr2-expressing myeloid cells exacerbated HFD-induced obesity, IR, glucose/lipid metabolic disturbances, and inflammation." (PMID 36984693, 2023). "Regarding the role in inflammatory-based diseases, FPR1 promotes malignant glioblastoma progression and FPR2/ALX is implicated in the pathogenesis of Alzheimer’s disease, wound healing, diabetes, obesity and AIDS." (PMID 35454990, 2022). "Dysfunction of FPR2 led to the development of spontaneous obesity, impaired macrophage function, and triggered kidney fibrosis, providing evidence of multiorgan defects in HFpEF in an obesogenic aging experimental model." (PMID 34409075, 2021). "Formyl peptide receptor 2 (FPR2) also plays a significant role in HFD-induced obesity, and the ablation of FPR2 reduces inflammation by inhibiting macrophage infiltration and M1 polarization in adipose tissue." (PMID 34360840, 2021). "A recent report suggests that the deletion of resolution sensor ALX/FPR2 develop age-related obesity and diastolic dysfunction in mice with HFpEF." (PMID 34409075, 2021). "The gene FPR2 binds to lipid mediators such as resolvin D1 for promoting resolution of inflammation, including the resolution of obesity-induced chronic low-grade inflammation." (PMID 31212707, 2019). "Rv D1 has been shown to prime the resolution process initiated by calorie restriction in obesity-induced steatohepatitis through FPR2." (PMID 31116781, 2019).
Obesity (continued). "Consistent with this, ALX/FPR2 and its proresolution agonists are defective in human diseases characterized by non resolving inflammation, such as asthma, obesity and atherosclerosis." (PMID 29044225, 2017). "Regarding its proinflammatory effect, FPR2 increases monocyte and neutrophil chemotaxis and recruitment and plays critical roles in high fat diet (HFD)-induced obesity and its associated complications by modulating inflammation mediated by macrophage M1 polarization." (PMID 35018584, 2022). "The authors revealed that Fpr2 deficiency reduced body weight gain in HFD-fed mice through enhancing energy expenditure, especially in skeletal muscle, and also reduced tissue and systemic inflammation in mice with diabetic-induced obesity by inhibiting macrophage infiltration and M1 polarization." (PMID 36984693, 2023). "Annexin A1 is known to have beneficial effects in islets by potentiating glucose‐stimulated insulin release and protecting against apoptosis, so its secretion from expanded adipose depots in obesity may lead to improved islet function via binding to the formylpeptide receptor FPR2." (PMID 36245259, 2022). "Interestingly, mice lacking the receptor FPR2 develop age-associated obesity and diastolic dysfunction." (PMID 33924323, 2021). "FPR2 is the primary target for LXA4 and has multiple roles in cardiometabolic diseases including in aging and obesity." (PMID 39563316, 2024). "Our findings that primary adipocytes express both fpr1 and fpr2, and direct addition of WKYMVm into primary adipocytes effectively modulates the expression of genes in lipid metabolism suggest that WKYMVm may act on primary adipocytes, resulting in the improvement of lipid metabolism in obesity." (PMID 37603580, 2023). "However, this property of Fpr2 was exploited by a metabolic disease for recruitment and M1 polarization of macrophages in white adipose in mice with HFD-induced obesity." (PMID 32038501, 2020).
atherosclerosis (18 papers, 2018 to 2025). A disease characterized by the build-up of fatty material and calcium deposition in the arterial wall resulting in partial or complete occlusion of the arterial lumen. "FPR2 promotes the migration and proliferation of smooth muscle cells in atherosclerosis and mediates pro-inflammatory responses." (PMID 38600259, 2024). "Again, formyl peptide receptor's (FPR) subtype FPR2 is involved in atherosclerosis as well as the stimulation of proinflammatory and proresolution responses, and atherosclerosis is linked with inflammatory responses." (PMID 36035865, 2022). "Overall, those findings highlight a failure in the resolution of inflammation in atherosclerosis, evidenced by decreased levels of proresolving ligands and increased levels of proinflammatory FPR2 agonists." (PMID 33804219, 2021). "FPR2 is upregulated in blood mononuclear cells from atherosclerosis patients and SAA stimulation induces macrophage foam cell formation, JNK activation and lectin-like oxidized low-density lipoprotein receptor 1 upregulation." (PMID 33804219, 2021). "In fact, in ApoE and FPR2 double-knock-out mice increased lesions size in early stages of atherosclerosis have been described." (PMID 33804219, 2021). "FPR2-SAA interaction contributes to atherosclerosis progression also by promoting the secretion of long pentraxin 3 (PTX3), an essential component of innate immunity, in human aortic endothelial cells." (PMID 33804219, 2021). "The author concluded that ALX/FPR2 signaling may play a dual role during atherosclerosis by (i) promoting disease progression and (ii) increasing plaque stability while facilitating fibrous cap formation." (PMID 40862723, 2025). "Additionally, another subtype, FPR2, can also increase macrophage infiltration in plaques, promoting the development of atherosclerosis, but it can also increase the collagen fiber content within plaques, thereby enhancing plaque stability." (PMID 39700090, 2024). "However, other ligands, such as serum amyloid A, stimulate the proinflammatory action of FPR2, which exacerbates atherosclerosis and diabetic retinopathy by producing proinflammatory cytokines." (PMID 40988882, 2024). "The results suggest a dual role of ALX/FPR2 signaling in atherosclerosis." (PMID 35563200, 2022). "Hence, ALX/FPR2 signaling has an ambivalent role since it can increase the development of atherosclerosis." (PMID 35328553, 2022). "This suggests that potential inflammation resolution induced by LXA4 signaling through FPR2 may be impaired in this atherosclerosis model, as result of the low biosynthesis of this agonist." (PMID 33804219, 2021). "For instance, the failure in the resolution of inflammation mediated by limited production of proresolving lipid FPR2 ligands, as well as the unmasking of proinflammatory FPR2 signaling, may be responsible for chronic inflammatory reactions in atherosclerosis." (PMID 33804219, 2021). "Restoring the proresolving FPR2 signaling may offer novel therapeutic options both in the prevention of atherosclerosis progression and in increasing atherosclerotic plaque stability." (PMID 33804219, 2021). "Other proresolving or anti-inflammatory FPR2 agonists are therapeutic in atherosclerosis." (PMID 33804219, 2021).
atherosclerosis (continued). "Our findings indicate that let-7f promotes hMSC tropism towards atheromas through the LL-37/FPR2 axis and demonstrate that hMSCs upon contact with human plaque environment develop a potentially athero-protective signature impacting the pathophysiology of atherosclerosis." (PMID 35238350, 2023). "For instance, through the activation of FPR2, A-SAA has been described to regulate leukocyte activation, atherosclerosis, pathogen recognition, bone formation and cell survival." (PMID 36817589, 2023). "Paradoxically, human studies show that FPR2 expression is increased in atherosclerosis in males but not females." (PMID 40988882, 2024). "However, another study reported increased lesion size in early stages of atherosclerosis in ApoE and ALX/FPR2 double-knock-out mice." (PMID 30487747, 2018).
breast carcinoma (18 papers, 2014 to 2025). "On the other hand, proliferation stimulation was observed in hepatocytes, in which AnxA1 was related to EGF, and in breast cancer; in the latter, it was associated with formyl peptide receptor (FPR2) binding and increased levels of cyclin D1." (PMID 24719523, 2014). "We here confirmed that B16F10 cells constitutively express FPR1 and FPR2, and data from the literature show that AnxA1 binds to both receptors and leads to cancer progression, such as breast cancer." (PMID 36766767, 2023). "For example, ANXA1 was shown to be involved in tumour microenvironment possibly by increasing M1 macrophages, and to control tumour growth and metastasis via its receptor FPR2 in breast cancer." (PMID 35770335, 2022). "It has been shown that ANXA1 by FPR2 activation, stimulates breast cancer proliferation." (PMID 30213113, 2018). "The authors found that FPR2 antagonists (WRW4 or Boc2) or siRNA-mediated downregulation of FPR2 decreased the proliferation rate of MCF-7 and MDA-MB-231 breast cancer cells." (PMID 40862723, 2025). "ANXA1 has been demonstrated to promote endothelial tube formation and enhance VEGF secretion by activating the formyl peptide receptor FPR2, and increased levels of ANXA1 correlate with angiogenesis in breast cancer." (PMID 38659028, 2024). "There were seven shared hub nodes (FPR2, CXCR4, FPR1, CX3CL1, GPR37, GABBR2 and PLCB1) between metastatic breast cancer cell lines." (PMID 35045088, 2022). "Protein-protein interaction (PPI) analysis revealed seven shared (PLCB1, FPR1, FPR2, CX3CL1, GABBR2, GPR37, and CXCR4) hub genes between brain and lung metastasis in breast cancer." (PMID 35045088, 2022). "E2F1 directly stimulated protease, serine S1 family member 22 (PRSS22) transcription, which facilitated efficient cleavage of Annexin A1 (ANXA1), producing an N-terminal peptide to activate formyl-peptide receptor-2 (FPR2)/ERK cascade, thus favoring the invasive phenotype in breast cancer." (PMID 39119602, 2024).
asthma (16 papers, 2012 to 2025). "Consistent with its role in resolving inflammation, altered ALX/FPR2 levels have been implicated in disease severity, such as for patients who have severe asthma." (PMID 40972651, 2025). "Additional supportive evidence from a clinical study in severe pediatric asthma reported reduction of lipoxin A4 levels and FPR2/ALX expression." (PMID 39720728, 2024). "Increased levels of FPR2 in sputum cells were also observed in intermittent asthma, whereas a reduced level of FPR2 was observed in severe asthma compared to healthy controls." (PMID 36142517, 2022). "Previous studies have reported that Anxa1 and FPR2 play an important role in the pathogenesis of asthma." (PMID 33193578, 2020). "There was a significant increase in the FPR2 expression of NK cells and ILC2s from patients with severe asthma compared with those with milder asthma." (PMID 32848759, 2020). "LXA4 and FPR2 levels are increased in patients with moderate asthma but are significantly decreased in patients with severe asthma." (PMID 33082511, 2020). "Defective LPX A4 generation and FPR2 insufficiency has been demonstrated to reduce the ability of inhaled corticosteroids to impair control of airway inflammation in children with severe asthma." (PMID 31116781, 2019). "In line with our findings, decreased FPR2 expression and LXA4 generation have been recently shown to be involved in a reduction in the ability of inhaled corticosteroids to impair control of airway inflammation in pediatric severe asthma patients." (PMID 29544524, 2018). "Patients with severe asthma have reduced levels of LXA4 and its receptor, ALX/FPR2." (PMID 28959799, 2017). "FPR2-related airway diseases and conditions include allergic inflammation, acute lung injury (ALI), lung injury induced by fat embolism syndrome, acute respiratory distress syndrome, ventilator-induced lung injury, asthma, aspirin-exacerbated respiratory disease (AERD), and COPD55,58–64." (PMID 33082511, 2020). "In addition, receptor FPR2 expression was increased in OVA-challenged mice, suggesting that ANXA1 may be involved in asthma pathogenesis." (PMID 29301525, 2018).
myocardial infarction (13 papers, 2019 to 2026). Gross necrosis of the myocardium, as a result of interruption of the blood supply to the area, as in coronary thrombosis. "Following myocardial infarction, FPR2-deficient mice had decreased numbers of resolving macrophages and increased numbers of neutrophils at the site of injury, indicating that FPR2 could play an important role in resolution following ischemic injury." (PMID 35039631, 2022). "Previously, FPR2 activation by a synthetic FPR2 agonist was shown to increase the number of pro-resolution macrophages in an animal model of myocardial infarction." (PMID 37237453, 2023). "FPR2 agonists can help improve the healing process after myocardial infarction, thus providing an innovative option for therapy." (PMID 35692878, 2022). "Of relevance here, FPR2 agonists are also cardioprotective in experimental models of myocardial infarction." (PMID 33924323, 2021). "The first-generation of FPR2 small-molecule agonists also show heart-protective properties in acute myocardial infarct and compound 43, a dual FPR1/FPR2 agonist, provides a high degree of protection in a model of heart failure." (PMID 33804219, 2021). "ALX/FPR2 activation limited myocardial scar after myocardial infarction." (PMID 35142983, 2022). "FPR2 agonists, such as compound 17b, BMS-986235, and WKYMVm, have demonstrated reparative activity and reduced immune dysregulation in experimental models of myocardial infarction (MI) and HF." (PMID 41486400, 2026). "In a murine model of myocardial infarction, ALX/FPR2 was expressed on PMN and macrophages." (PMID 35142983, 2022). "FPR2 agonist has been shown to promote NK cell migration through ERK activation, and to provides cardiac protection through mobilization of circulating angiogenic cells after myocardial infarction in murine models." (PMID 31116781, 2019). "In left ventricle (LV) and splenic remodeling post-myocardial infarction (MI), the RvD1-group showed an early exit of neutrophils from LV and spleen at day 5 after MI with the increased expression of the LXA4 receptor (ALX; synonym formyl peptide receptor; FPR2) compared to the MI-saline group." (PMID 33321955, 2020).